RNF216P1 (ring finger protein 216 pseudogene 1)
Synonyms: RNF216L; hCG2040556
Gene: Long non-coding RNA gene on chromosome 7 (4,973,988 to 5,040,675, forward strand). Ensembl gene ENSG00000196204.
Diseases named in the same sentence as RNF216P1 in open-access papers:
RNF216P1 is named in the same sentence as 2 diseases in open-access papers, as found by Europe PMC text mining. Sharing a sentence is not in itself a finding about the gene and the disease.
RNF216P1 shares sentences with these, for which no sentence is quoted: autism (1 paper); hepatoma (1).